TSC2 (TSC complex subunit 2)
Diseases named in the same sentence as TSC2 in open-access papers (continued):
Sharing a sentence is not in itself a finding about the gene and the disease.
tuberous sclerosis (continued). "Mutations of tumor suppressor genes tuberous sclerosis complex 1 (TSC1) and TSC2 are linked to the pathobiology of hamartoma syndrome Tuberous Sclerosis (TSC) and pulmonary lymphangioleiomyomatosis (LAM)." (PMID 25360538, 2014). "Mutations in the TSC2 (tuberous sclerosis 2) gene cause an autosomal dominant disorder, tuberous sclerosis complex (TSC)." (PMID 24748662, 2014). "Germline and somatic biallelic mutations of the Tuberous sclerosis complex (TSC) 1 and TSC2 gene products cause TSC, an autosomal dominant multifocal hamartomatosis with variable neurological manifestations." (PMID 24633152, 2014). "Tuberous sclerosis complex (TSC) is a genetic disorder affecting about 1 in 6,000 newborns caused by inactivating mutations in Tsc1or Tsc2, encoding hamartin and tuberin, respectively." (PMID 23696872, 2013). "The genes that encode these two subunits, TSC1 and TSC2, carry dominant mutations that produce tuberous sclerosis (TSC), another important syndromic form of ASD that impacts synaptic calcium signaling." (PMID 24204377, 2013). "Inactivating mutations in either TSC1 or TSC2 result in Tuberous Sclerosis Complex (TSC), characterized by abnormal cortical development and seizures." (PMID 22567115, 2012). "Tuberous sclerosis (TSC) is an autosomal dominant disease due to heterozygous mutations in TSC1 on chromosome 9q34 or TSC2 on chromosome 16p13." (PMID 19333415, 2009). "Tuberous sclerosis complex is an autosomal dominant monogenic disease, which is caused by the abnormal structure and function of TSC1/TSC2 complex caused by TSC1 or TSC2 mutation." (PMID 40595935, 2025). "Unfortunately, these drugs work on a specific cohort of tuberous sclerosis patients, harboring rare mutations in TSC1/TSC2, resulting in overactivating the PI3K-AKT–MTOR pathway." (PMID 40529445, 2025). "Genetic testing for mutations in the TSC1 and TSC2 genes is important, given that LAM has been associated with tuberous sclerosis." (PMID 40761985, 2025). "Mutations in genes such as TSC1, TSC2, and MTOR itself, which lead to hyperactivation of the mTOR pathway, are central to the pathogenesis of diseases like tuberous sclerosis complex (TSC) and certain forms of cancer." (PMID 40358185, 2025). "The coexistence of tuberous sclerosis complex and autosomal dominant polycystic kidney disease due to a contiguous gene deletioninvolving TSC2 and PKD1 represents a rare but significant genetic syndrome." (PMID 40822828, 2025). "Tuberous sclerosis complex is a genetic disorder characterised by the formation of benign tumours in multiple organs, primarily due to pathogenic variants in the TSC1 and TSC2 tumour suppressor genes." (PMID 40655946, 2025). "Subependymal giant cell astrocytoma (SEGA) is a rare, low‐grade glioma typically associated with tuberous sclerosis (TS) and mutations in the TSC1 or TSC2 genes." (PMID 39492623, 2025). "Mutations in TSC1 or TSC2 genes disrupt the function of TSC1-TSC2 complex, leading to mTORC1 hyperactivation, which is thought to cause tuberous sclerosis complex." (PMID 39901197, 2025). "TSC1 and TSC2 respectively encode for the hamartin (TSC1) and tuberin (TSC2) proteins, which together form the tuberous sclerosis complex." (PMID 39456169, 2024). "TSC2/PKD1 contiguous gene syndrome is caused by deletions involving the TSC2 and PKD1 genes that lead to tuberous sclerosis complex and autosomal dominant polycystic kidney disease." (PMID 39323690, 2024). "We here used a mouse model for tuberous sclerosis (TS) carrying a heterozygous deletion of the Tsc2 gene." (PMID 39192595, 2024).
tuberous sclerosis (continued). "Here, we describe an unprecedented case of a dual diagnosis of Tuberous sclerosis (TSC2; #613254; OMIM) and KBG syndrome (#148050; OMIM) because of one single genomic event (inversion)." (PMID 38253421, 2024). "Tuberous Sclerosis (TS) is a rare, multisystem genetic disease caused by mutations in the TSC1 and TSC2 genes, leading to abnormalities in cell differentiation and proliferation." (PMID 38311784, 2024). "Tuberous sclerosis is another AD “tumor syndrome,” caused by pathogenic variants in the TSC1 or TSC2 tumor suppressor genes, tuberin and hamartin, that inhibit the mammalian target of rapamycin (mTOR) pathway." (PMID 37644229, 2024). "For example, IL-6 is significantly upregulated and plays a critical role in the development of tuberous sclerosis complex, a benign tumor syndrome caused by aberrant mTORC1 activation due to the loss of either TSC1 or TSC2." (PMID 38610018, 2024). "Mutations in the TSC2 gene and mutations in the adjacent PKD1 gene lead to the overlapping syndrome of tuberous sclerosis and polycystic kidney disease." (PMID 39201746, 2024). "A good example is Tuberous Sclerosis Complex, a rare developmental disorder caused by mutations in TSC1 and TSC2." (PMID 37255597, 2023). "In LAM, larger and more frequent angiomyolipomas are often linked to TSC2 mutations and present a slightly distinct phenotype compared to TSC1- and TSC2-related diseases in tuberous sclerosis." (PMID 37719610, 2023). "TSC2 was detected in 65% of a cohort of patients with genetically confirmed tuberous sclerosis complex, including seizures, skin manifestations, and developmental delay." (PMID 37628333, 2023). "Tuberous sclerosis, or TSC, is a systemic neurological disorder caused by mutations in TSC1 or TSC2 that lead to benign tumors in the brain and other tissues." (PMID 36675042, 2023). "In addition, patients with tuberous sclerosis (TSC), a genetic disorder with mutations in the Tsc1 or Tsc2, have a high prevalence of ASD." (PMID 37794488, 2023). "Tuberous sclerosis complex, an autosomal dominant disorder, characterized by mutations in TSC1 or TSC2, causes hamartoma formation in various of the organ systems." (PMID 36231025, 2022). "Previous studies have targeted tuberous sclerosis complex (TSC1 and TSC2) to model tuberous sclerosis, a multi-organ disorder characterized by the growth of non-cancerous tumors." (PMID 35359577, 2022). "Human tuberous sclerosis (TSC) is mainly caused by genetic mutations of tuberous TSC1or TSC2." (PMID 36465179, 2022). "The TSC2 gene is located on chromosome 16p13.3 and was identified as a disease-causing gene of TSC in 1993 (European Chromosome 16 Tuberous Sclerosis C, 1993)." (PMID 35692821, 2022). "The TSC1 gene on chromosome 9q34 was firstdiscovered in 1997 (van Slegtenhorst etal., 1997), though the TSC2 gene onchromosome 16p13.3 was discovered in 1993 (EuropeanChromosome 16 Tuberous Sclerosis Consortium, 1993)." (PMID 35638823, 2022). "The mTOR pathway is also involved in the pathogenesis of tuberous sclerosis complex (TSC), which results from mutations in the TSC1 (encoding hamartin) or TSC2 (encoding tuberin) gene." (PMID 36197220, 2022). "Tuberous sclerosis TSC1/TSC2 (hamartin/tuberin) complex functions as a heterodimer and has pivotal roles in mediating the effect of growth factors, energy, and oxygen on mTORC1." (PMID 34572595, 2021). "Methodology: We analysed peripheral blood from 10 control individuals and 14 TSC2 paediatric patients (10 from the Tuberous Sclerosis Alliance Biosample Repository and 4 from Hospital São João), carrying different TSC2 pathogenic variants." (PMID 33530161, 2021). "The TSC1 and TSC2 genes are tumor suppressor genes, and mutations of either TSC1 or TSC2 lead to the tuberous sclerosis syndrome, which is a multisystem disorder characterized by benign tumors in many organs, including lung, heart, kidney, and brain." (PMID 33445779, 2021).
tuberous sclerosis (continued). "In tuberous sclerosis complex (TSC), Tsc2 mutations are associated with more severe disease manifestations than Tsc1 mutations and the role of extracellular vesicles (EVs) in this context is not yet studied." (PMID 34262466, 2021). "In patients with tuberous sclerosis complex suffering from severe and treatment-resistant epilepsy, the mTOR pathway is hyperactivated due to mutations in TSC1 and TSC2 genes." (PMID 33859552, 2021). "Tuberous sclerosis, another common cause of syndromic ID, is associated with increased risk of brain tumor due to mutations of TSC1 and TSC2." (PMID 34673770, 2021). "Tsc2+/− and Tsc1 homozygous mutant mice (a model of tuberous sclerosis), were treated with rapamycin, rescuing spatial learning and context discrimination deficits together with neurological findings." (PMID 34200511, 2021). "To examine this response in vivo, we employed a mouse model of tuberous sclerosis complex involving xenograft tumors derived from the rat TSC2-/- tumor cell line ELT3." (PMID 33646118, 2021). "Mutations in TSC1 and TSC2 genes cause tuberous sclerosis (TSC)." (PMID 34204582, 2021). "Mutations in TSC2 may cause Tuberous Sclerosis Complex (TSC) (MIM 191092), an autosomal dominant disorder characterized by hamartomas in several organ systems." (PMID 34442399, 2021). "Tuberous Sclerosis, also known as Tuberous Sclerosis Complex (TSC) is a rare genetic disorder caused by germline inactivating mutations in either the TSC1 or TSC2 genes." (PMID 32087199, 2020). "We studied sleep duration in three mouse models by means of home-cage monitoring: Tsc2+/− (tuberous sclerosis complex), oxytocin receptor (Oxtr) knockout (KO) (autism spectrum disorders), and Shank3 e4-9 KO (Phelan–McDermid syndrome)." (PMID 33396736, 2020). "Tuberous sclerosis (TSC) tumor suppressor complex (TSC1/TSC2) indirectly inhibits mTORC1 activity by negatively regulating the activity of Rheb via the GTPase-activating protein (GAP) activity of TSC2." (PMID 32974004, 2020). "In 2012, the Tuberous Sclerosis Complex Surveillance and Management recommendations were updated to include the identification of a heterozygous pathogenic variant in either TSC1 or TSC2 by molecular genetic testing as meeting criteria for a definitive diagnosis of TSC." (PMID 32383331, 2020). "An association with tuberous sclerosis (TSC-LAM complex) is known, with mutations of two known genes (TSC1 and TSC2) found in these cases." (PMID 32471113, 2020). "In tuberous sclerosis Tsc2+/− mutant mice, a well-known intellectual disability, epilepsy and ASD animal model, the application CDPPB is able to restore normal mGluR-LTD." (PMID 33229412, 2020). "Deletions larger than 2000 kb including the PKD1 and TSC2 genes lead to severe MR with polycystic kidney disease and tuberous sclerosis, respectively." (PMID 32005695, 2020). "AKT regulates the mTORC1 complex by phosphorylating and inhibiting the TSC-2 gene (Tuberous Sclerosis 2), which is a GTP-ase activating protein (GAP) that binds to TSC-1 (Tuberin) forming a complex and blocking the G Rheb protein." (PMID 32850962, 2020). "A mouse model of Tuberous Sclerosis Tsc2+/– exhibits reduced mGluR-LTD (LTD) in the hippocampus and altered levels of mGluR signaling Arc (activity-regulated cytoskeleton-associated) protein, which is crucial for AMPAR internalization in cerebellar LTD." (PMID 33519379, 2020). "For example, thus far cystic fibrosis had only been associated with variants in CFTR, while tuberous sclerosis had only been associated with TSC1 and TSC2." (PMID 30987386, 2019). "For example, in patients with a clinical diagnosis of tuberous sclerosis, a spectrum of heterozygous variants affecting TSC1 and TSC2 had been described." (PMID 30987386, 2019). "These mouse models have shown that dysregulation of the mTOR signaling pathways, induced by Tsc1 and Tsc2 inactivation, results in a Tuberous Sclerosis-like phenotype." (PMID 31245336, 2019).
tuberous sclerosis (continued). "The deletion region comprises TSC2, PKD1, TBC1D24 and ABCA3 genes and mutations of these genes are associated with tuberous sclerosis complex, autosomal dominant polycystic kidney disease type 1 (ADPKD1) or familial infantile myoclonic epilepsy." (PMID 31060568, 2019). "Phosphorylation of TSC2 by Erk promotes dissociation of the tuberous sclerosis complex and attenuates TSC2-mediated inhibition of mTOR in cells." (PMID 30943918, 2019). "A TSC2/PKD1 contiguous gene syndrome, which is caused by a chromosomal mutation that disrupts both the TSC2 and PKD1 genes, has been identified in patients with tuberous sclerosis complex and severe early-onset autosomal dominant polycystic kidney disease." (PMID 31870441, 2019). "Tsc2−/− mice mimicking tuberous sclerosis are an exception because in these animals it is the activation of mGlu5 receptors that corrects the pathological phenotype." (PMID 29615849, 2018). "Tuberous sclerosis results from mutations in TSC1 and TSC2, which are direct negative regulators of the mTORC1 complex." (PMID 30083288, 2018). "We also compared aspects of our patient's condition with the clinical features of tuberous sclerosis (TSC), which is an autosomal neurocutaneous syndrome caused by mutations in the TSC1/TSC2 genes." (PMID 30332768, 2018). "p-AMPK can phosphorylate TSC2 at S1387 to activate the tuberous sclerosis complex which inhibits p-mTOR40,42." (PMID 30250195, 2018). "Tuberous sclerosis complex is a genetic disease caused by either TSC1 or TSC2 mutation, leading to mTORC1 hyperactivation, and most patients with this disease have TSC2 mutations." (PMID 30266942, 2018). "About 30-40% of women with Tuberous Sclerosis Complex (TSC), a genetic disorder caused by TSC1 and TSC2 mutations, have radiographic evidence of LAM." (PMID 28410230, 2017). "Tuberous sclerosis is caused by mutations in one of two tumor suppressor genes:TSC1 (9q34) and TSC2 (16p13.3)." (PMID 28222202, 2017). "Tuberous sclerosis complex is a multisystem disease in which inactivation of the TSC1 or TSC2 gene leads to mTORC1 hyperactivation." (PMID 28498820, 2017). "Tuberous sclerosis (TS), a hereditary autosomal syndrome caused by defects in either TSC1 or TSC2 genes, is characterized by a wide spectrum of clinical manifestations in multiple organs." (PMID 28646232, 2017). "Sirolimus has shown promising effects in patients with inactivating mutations in TSC1, TSC2 and STK11 in hamartoma syndromes such as tuberous sclerosis complex and Peutz-Jeghers Syndrome." (PMID 26859683, 2016). "Tuberous sclerosis complexes (TSCs) normally inhibit Rheb-directed mTOR activation, and mutations in TSC proteins (TSC1-hamartin, TSC2-tuberin) constitutively activate Rheb-mTOR-pS6K and increase cell size." (PMID 27795403, 2016). "Tuberous sclerosis (TSC) is a monogenic disease resulting from defects of the tuberin (TSC2) or hamartin (TSC1) genes." (PMID 27680012, 2016). "The TSC2 gene encodes tuberin and together with TSC1, encoding for hamartin, causes the tuberous sclerosis complex (TSC)." (PMID 26077033, 2015). "Mutations in the TSC1 and TSC2 genes cause tuberous sclerosis complex (TSC), a genetic disease often associated with epilepsy, intellectual disability, and autism, and characterized by the presence of anatomical malformations in the brain as well as tumors in other organs." (PMID 26693177, 2015). "Typically rhabdomyomas are multiple lesions and usually regress spontaneously but are often associated with tuberous sclerosis complex (TSC), an autosomal dominant multisystem disorder caused by mutations in either of the two genes, TSC1 or TSC2." (PMID 24884933, 2014).
tuberous sclerosis (continued). "When TSC2 protein is lost, (e.g. in tuberous sclerosis), mTOR remains constitutively activated to drive cell growth." (PMID 24318044, 2014). "Neurofibromatosis type 1 (NF-1) and tuberous sclerosis (TS) are autosomal dominant tumor susceptibility syndromes caused by inactivating mutations in the tumor suppressor genes NF1 and TSC1 and TSC2, respectively." (PMID 25092520, 2014). "The TSC2 gene was initially identified in the development of tuberous sclerosis, a systemic disorder characterised by the development of benign hamartomas." (PMID 24318044, 2014). "There is a strong association between PEComas and tuberous sclerosis, which is due to the loss of tumor suppressor genes TSC1 or TSC2." (PMID 23984176, 2013). "While their genetic determinants are different (TSC1/TSC2 for tuberous sclerosis and FMR1 for fragile X syndrome), their gene products both regulate protein synthesis in neurons." (PMID 23935565, 2013). "Tuberous sclerosis (TS) is a dominant disorder produced by mutations affecting one of two proteins, TSC1 or TSC2." (PMID 22319582, 2012). "Overexpression of TSC1 or TSC2 led to reduction of Wnt-induced β-catenin signaling, whereas mutations in TSC1 or TSC2, as found in tuberous sclerosis patients, led to increased canonical Wnt signaling." (PMID 23083465, 2012). "More than half of the renal AML are considered to be associated with tuberous sclerosis which features the loss of heterozygosity at TSC1 (9q34) and TSC2 (16p13), while it is estimated to be 5–15% in the liver." (PMID 23320180, 2012). "Tuberous sclerosis complex (TSC) is caused by a mutation of either the Tsc1 or Tsc2 gene." (PMID 22848848, 2012). "Hyperactivation of the TOR pathway by mutations in the upstream TOR inhibitors TSC1 (tuberous sclerosis complex 1) or TSC2 promotes benign tumors and neurological and behavioral deficits, a syndrome known as tuberous sclerosis (TS)." (PMID 22319582, 2012). "In prior studies, the prevalence of sporadic tuberous sclerosis was 60-70% of the cases based on genetic (TSC1 or TSC2)." (PMID 24665269, 2012). "Another example is tuberous sclerosis (TSC), a genetic disorder resulting from mutation in one of the two tumor suppressor genes, TSC1 or TSC2, that often give rise to multiple neurological deficits such as epilepsy, mental retardation and autism." (PMID 20230616, 2010). "Tuberous Sclerosis Complex is genetically determined with an autosomal dominant inheritance and is caused by inactivating mutations in either the TSC1 or TSC2 genes." (PMID 19506736, 2008). "Tuberous sclerosis complex is a dominant genetic disorder produced by mutations in either of two tumor suppressor genes, TSC1 and TSC2; it is characterized by hamartomatous tumors, and is associated with severe neurological and behavioral disturbances." (PMID 17440611, 2007). "TSC1 and TSC2 constitute the tuberous sclerosis complex and hamartin and tuberin constitute their respective protein products." (PMID 16412252, 2006). "Nevertheless, further research is required to elucidate how different post-translational modifications affect TSC1 and TSC2 protein regulation, which could greatly influence the development of tuberous sclerosis complex treatments." (PMID 39901197, 2025). "TSC-LAM occurs in the setting of tuberous sclerosis complex (TSC), a multisystem genetic disorder characterized by mutations in TSC1 and TSC2, and is associated with additional clinical features including shagreen patches, facial angiofibromas, and recurrent seizures." (PMID 40761985, 2025). "The study aims to investigate the clinical, imaging, and molecular characteristics of patients diagnosed with tuberous sclerosis and to explore the correlation between specific genetic mutations (TSC1 and TSC2 genes) and the severity of clinical manifestations." (PMID 40364023, 2025). "Mutations in TSC1 or TSC2 cause tuberous sclerosis complex, but no germline mutations in TBC1D7 have been found in patients." (PMID 39901197, 2025).